AJM1 (apical junction component 1 homolog)
Description:
May be involved in the control of adherens junction integrity.
Synonyms: C9orf172; ajm-1
Tractability: Antibody: UniProt places it where antibodies can reach, with medium confidence; its Gene Ontology location is reachable by antibodies, with medium confidence; the Human Protein Atlas places it where antibodies can reach.
Gene: Protein-coding gene on chromosome 9 (136,842,478 to 136,848,801, forward strand). Ensembl gene ENSG00000232434.
Subcellular location: Apical cell membrane; Cell projection, cilium; Cell junction, adherens junction
Subcellular location (Human Protein Atlas): Golgi apparatus; Plasma membrane
Gene Ontology:
Biological process: cell-cell junction organization
Cellular component: apical junction complex; apical plasma membrane; plasma membrane; adherens junction; cilium
Genetic constraint (gnomAD): Loss-of-function variants: 20 observed, 25.02 expected, observed/expected ratio (o/e) 0.8, 90% interval 0.56 to 1.16. The synonymous counts are far from expectation, so gnomAD's model fits this gene poorly and the ratio says little. Missense variants: 1,004 observed, 843.01 expected, observed/expected ratio (o/e) 1.19, 90% interval 1.13 to 1.25. Synonymous variants: 564 observed, 380.89 expected, observed/expected ratio (o/e) 1.48, 90% interval 1.38 to 1.59.
Homologues: Orthologues: chimpanzee AJM1 (99% identical), macaque AJM1 (97% identical), dog AJM1 (90% identical), pig AJM1 (90% identical), mouse Ajm1 (87% identical), rat Ajm1 (86% identical), tropical clawed frog ajm1 (55% identical), zebrafish unm_hu7912 (44% identical).
Diseases named in the same sentence as AJM1 in open-access papers:
AJM1 is named in the same sentence as 5 diseases in open-access papers, as found by Europe PMC text mining. Sharing a sentence is not in itself a finding about the gene and the disease. The quoted sentences say what the papers report.
cyst (1 paper, 2013). A sac-like closed membranous structure that may be empty or contain fluid or amorphous material. "This localization contrasts with that in intestinal cells and most other cyst cells, where HMR-1/E-cadherin is predominantly at the midline or apical surface in association with apical junction proteins such as AJM-1." (PMID 24039608, 2013).
infection (2 papers, 2012 to 2016). The state of being infected such as from the introduction of a foreign agent such as serum, vaccine, antigenic substance or organism. "Here we also provide evidence for the first time, that SU159 nematodes, expressing the GFP-tagged apical epithelial marker AJM-1, displayed a continuous and unbreached staining of the intestinal epithelium upon infection with S. Typhimurium." (PMID 23028994, 2012). "OG1RF infection did not modulate dlg-1, ajm-1, or let-413 expression." (PMID 26769134, 2016).
intestinal disease (1 paper, 2025). "Recent evidence has linked AJM1 expression to intestinal disease models and toxicological stress responses." (PMID 41209574, 2025).
tumor (1 paper, 2025). "The protective function of AJM1 is further supported by its potential role in modulating the tumor microenvironment." (PMID 41209574, 2025). "Moreover, the observed link between AJM1 downregulation and increased tumor cell proliferation underscores the potential importance of epithelial junction regulation as a therapeutic target in PAAD." (PMID 41209574, 2025). "In this study, qPCR analyses revealed significantly higher AJM1 expression in paracancerous tissues compared to tumor tissues, suggesting that its downregulation may contribute to tumor initiation and progression." (PMID 41209574, 2025). "Using 33 pairs of PAAD tumor and adjacent non-tumor tissue samples, qPCR analyses confirmed that AJM1 expression was significantly higher in paracancerous tissues compared with tumor tissues." (PMID 41209574, 2025).
AJM1 also shares sentences with these, for which no sentence is quoted: pancreatic adenocarcinoma (1 paper).